MEFV (MEFV innate immunity regulator, pyrin)
Diseases named in the same sentence as MEFV in open-access papers (continued):
Sharing a sentence is not in itself a finding about the gene and the disease.
Arthritis (20 papers, 2013 to 2026). Inflammation of a joint. "FMF, being an AID, is caused by MEFV gene mutation and is characterized by self-limited episodes of fever and systemic inflammation, usually with pleural and abdominal serositis and arthritis." (PMID 40041636, 2025). "These patients diagnosed as idiopathic RSH with relapsing and recurrent arthritis of hip showed MEFV gene mutations that include R761H, V726A, and A744S in heterozygote form which are not normal variants of healthy people in this area." (PMID 32778116, 2020). "Screening of MEFV mutations in different rheumatic diseases showed its effective role in these patients with arthritis other than FMF." (PMID 32778116, 2020). "Our results indicate that the later-onset FMF patients had a lower percentage of MEFV mutations in exon 10 and predominantly presented arthritis and myalgia." (PMID 30458853, 2018). "FMF is caused by gain-of-function mutations in the MEFV gene, which encodes the pyrin protein, FMF is characterized by recurrent, short episodes of fever, peritonitis, pleuritis, arthritis, and rash, with oral manifestations occurring in up to 10% of cases." (PMID 39274292, 2024). "Among the polymorphisms found more frequently in AS patients with arthritis, JAK2 rs7857730, IL-23R rs11209008 and rs10489630, CYP1B1 rs1056836, NELL1 rs8176786, KL rs564481, MEFV rs224204, IL-2RB rs743777, and IL-1A rs1800587 have been described." (PMID 35629038, 2022). "In another study, MEFV mutation was found in 34% of 80 IgAV patients and those with the mutation were younger at the time of diagnosis of vasculitis and had more arthritis and subcutaneous edema than those without the mutation." (PMID 40195185, 2025). "While studies suggest that IgAV patients with MEFV mutations experience more arthritis and edema, no research has examined IL‐1 levels in this group." (PMID 40590520, 2025). "On the basis of possible role of MEFV gene in different rheumatic disease RSH could be considered as a MEFV gene related arthritis." (PMID 32778116, 2020). "This study reports three non-FMF patients with heterozygous MEFV gene mutations and an extraordinary arthritis as a recurrent synovitis of hip (RSH)." (PMID 32778116, 2020). "On the basis of possible role of MEFV gene in different rheumatic disease, MEFV gene related arthritis may be considered as a background of RSH particularly in Mediterranean area." (PMID 32778116, 2020). "In addition, patients carrying mutations in the MEFV gene were found to be younger and more likely to have arthritis and edema compared to those without mutations." (PMID 40590520, 2025).
amyloidosis (17 papers, 2017 to 2025). A disorder characterized by the localized or diffuse accumulation of amyloid protein in various anatomic sites. "Further studies are needed to clarify the potential role of the MEFV and non-MEFV variants, treatment, and environmental factors on the amyloid burden in patients with AA." (PMID 40593362, 2025). "The extensive genetic testing of genes associated with amyloidosis and (auto)inflammatory conditions found only variant K695R in MEFV gene." (PMID 40167786, 2025). "Modifying loci outside of the MEFV gene, including the MHC class I chain-related gene A (MICA) or SAA-1 alpha/alpha alleles, have also been shown to affect age of onset, and risk of developing amyloidosis, respectively, in those with existing MEFV mutations." (PMID 37865787, 2023). "The information of MEFV mutation status in patients with amyloidosis and its relationship with the clinical course was of importance." (PMID 36128216, 2022). "Patient with the MEFV gene p.Met694Val variant was the youngest one among the three cases with amyloidosis." (PMID 36128216, 2022). "The presence of accompanying factors such as heterozygosity for the MEFV variants and history of tuberculosis may facilitate the development of amyloidosis in patients with PsA." (PMID 36128216, 2022). "Furthermore, asymptomatic MEFV mutation carriers also have an increased SAA concentration potentially leading to the development of amyloidosis." (PMID 33679725, 2020). "Therefore, the risk of developing AA-A constitutes a complex issue, and it can be speculated that additional factors beyond the MEFV variants may contribute to the overall risk of amyloidosis." (PMID 40593362, 2025). "Additionally, median age at the diagnosis of AA amyloidosis and baseline creatinine levels were significantly lower while the duration of amyloidosis and baseline eGFR levels were significantly higher in patients with a homozygous p.M694V variant compared with the patients with other MEFV variants." (PMID 37738242, 2024). "Without other polymorphisms in the MEFV gene, the presentation of amyloidosis of our patient may or may not have been related to the heterozygous E148Q mutation." (PMID 28499374, 2017). "On the other hand, in a series of secondary amyloidosis cases from France, 15.3% of the patients did not have any mutations in the MEFV gene or in other autoinflammatory disease (AID) genes, suggesting that unknown factors may contribute to the development of amyloidosis." (PMID 40512183, 2025).
inflammatory bowel disease (13 papers, 2009 to 2025). A spectrum of small and large bowel inflammatory diseases of unknown etiology. "Associations have been observed between MEFV and autoimmune diseases, including systemic lupus erythematosus, rheumatoid arthritis and inflammatory bowel disease." (PMID 28800602, 2017). "Several studies reported an increase frequency of MEFV mutations among children of vasculitic and rheumatic diseases, like inflammatory bowel disease (IBD), polyarteritis nodosa (PAN), HSP and juvenile idiopathic arthritis (JIA)." (PMID 25232290, 2014). "Other inflammatory and autoimmune disorders have been recently associated with FMF and MEFV gene mutations, probably due to mutual dysregulations in the immune system, such as inflammatory bowel disease (IBD), ankylosing spondylitis, Behçet’s disease, multiple sclerosis, and rheumatoid arthritis." (PMID 40041636, 2025). "However, cases of inflammatory bowel disease associated with MEFV gene mutations have been reported and have attracted attention as a new disease concept, particularly in Japan, owing to the significant therapeutic effect of colchicine." (PMID 37176572, 2023). "We therefore sought to evaluate MEFV as an inflammatory bowel disease (IBD) susceptibility gene." (PMID 19784369, 2009). "Noteworthy, inflammatory bowel diseases seem to be more frequent and severe in patients with FMF and, conversely, the rate of MEFV mutations has been found higher in subjects diagnosed with inflammatory bowel diseases." (PMID 32082075, 2019). "For example, single nucleotide polymorphisms (SNPs) in the MEFV gene, involved in inflammation, have been linked to alterations in the microbial community structure of the human gut, and IBD (Inflammatory Bowel Disease)-risk loci are also associated with changes in gut microbiota composition." (PMID 36979663, 2023). "MEFV gene mutations have also been associated with non-FMF inflammatory diseases, including inflammatory bowel disease, rheumatoid arthritis, fibromyalgia syndrome, Behçet’s disease, ulcerative colitis, ankylosing spondylitis, and juvenile idiopathic arthritis." (PMID 37865787, 2023).
Behçet’s disease (11 papers, 2008 to 2025). "Patients with other inflammatory conditions as Behcet’s disease and tuberculosis have been found to test positive for MEFV gene mutation." (PMID 24433404, 2014). "The MEFV nsSNP rs61752717 is also associated with Behçet’s Disease (BD)." (PMID 30946743, 2019). "Behçet’s disease is also associated with MEFV polymorphisms, and Behçet’s disease cases carrying MEFV variants have more severe disease, suggesting that autoinflammation may also contribute to its development." (PMID 30946743, 2019). "It has been suggested that MEFV is a predisposing factor for Behçet's disease." (PMID 18576390, 2008).
periodic fever syndrome (11 papers, 2018 to 2023). Fevers of unknown etiology recurring over months or years. "S-11 presented with recurrent fever with joint pain, and periodic fever syndrome was considered, which is related to the MEFV mutation." (PMID 35096640, 2021). "In these patients, a genetic examination was carried out for monogenic periodic fever syndromes and the occurrence of non-pathogenic variants in MEFV and MVK genes were confirmed." (PMID 38143757, 2023).
autoinflammatory syndrome (10 papers, 2015 to 2025). A group of disorders of the innate immune system characterized by attacks of seemingly unprovoked inflammation without significant levels of either autoantibodies or autoreactive T cells more characteristic of autoimmune disease. "Future work should catalogue similar cases of compound heterozygous mutations of MEFV and NOD2/CARD15 to define the influence of genetic variation on disease presentation of autoinflammatory syndromes." (PMID 35591901, 2022). "Similar to MEFV, patients with MVK deficiency suffer from an autoinflammatory syndrome characterized by recurrent episodes of fever, arthralgia, lymphadenopathy, and splenomegaly." (PMID 36524121, 2022). "IL-1β, IL-18, and IL-33 were within normal limits or undetectable, and no mutations were found in genes related to the pathogenesis of autoinflammatory syndromes (MEFV, MVK, TNFRSF1A, NLRP3, and NLRP12)." (PMID 34829952, 2021). "In a previous study, using a next generation sequencing approach, we found many rare variants and some functional polymorphisms in genes related to autoinflammatory syndromes (AID): CECR1, MEFV, MVK, NLRP3, NOD2, PSTPIP1 and TNFRSF1A in our BD cohort." (PMID 30808881, 2019). "We describe a case of an autoinflammatory syndrome with a FMF-like presentation characterized by recurrent fevers, colchicine resistance, tocilizumab sensitivity and novel compound heterozygous mutations in the MEFV and NOD2 genes." (PMID 35591901, 2022). "This case identifies novel heterozygous variants in the MEFV and NOD2 genes that might have pathogenic significance in autoinflammatory syndromes." (PMID 35591901, 2022).
juvenile idiopathic arthritis (10 papers, 2008 to 2023). Juvenile idiopathic arthritis (JIA) is the term used to describe a group of inflammatory articular disorders of unknown cause that begin before the age of 16 and last over 6 weeks. "The allele frequencies of MEFV mutations were found to be 19.27%, in Turkish children with juvenile idiopathic arthritis which was higher than the general population." (PMID 32778116, 2020). "Furthermore, it has been reported that the presence of MEFV gene mutations might be a susceptibility factor for various inflammatory diseases, such as juvenile idiopathic arthritis (JIA)." (PMID 35480407, 2022). "The relationship between MEFV mutations and some rheumatic diseases such as juvenile idiopathic arthritis (JIA), RA, ankylosing spondylitis, systemic lupus erythematosus (SLE), Sjögren's syndrome, and polymyositis has been detected." (PMID 24455383, 2013).
vasculitis (10 papers, 2011 to 2025). "Due to an increased frequency of vasculitis in FMF patients, many investigators have studied MEFV mutations in patients with HSP." (PMID 25232290, 2014). "In conclusion, FMF, particularly when supported by two pathogenic MEFV mutations, could predispose to IgA vasculitis, or a PAN-like vasculitis with more perirenal bleeding and CNS involvement." (PMID 31031761, 2019).
PFAPA syndrome (9 papers, 2014 to 2024). An auto inflammatory syndrome characterized by recurrent febrile episodes associated with aphthous stomatitis, pharyngitis and cervical adenitis. "The underlying pathogenesis of PFAPA syndrome and the genotype-phenotype correlation in MEFV variants are both not fully understood." (PMID 36777733, 2023). "The rate of MEFV gene mutations in patients with PFAPA syndrome is also higher than in the general population." (PMID 36045426, 2022). "Some studies in the literature have reported an increased frequency of Mediterranean Fever (MEFV) gene mutations in patients with PFAPA syndrome." (PMID 32338845, 2020). "Methods: 21 patients with PFAPA syndrome who had diagnostic criteria were enrolled in this study and 12 common MEFV gene mutations i.e. P369S, F479L, M680I (G/C), M680I (G/A), I692del, M694V, M694I, K695R, V726A, A744S, R761H, E148Q evaluated." (PMID 25793047, 2014). "P040 Is the MEFV heterozygosity a predisposing factor for Pfapa syndrome phenotype?" (PMID 37848930, 2023). "MEFV heterozygosity is more associated with PFAPA syndrome phenotype." (PMID 37848930, 2023). "Types of MEFV gene mutations are important in therapeutic response.In studies that emphasize the effect of colchicine on patients with PFAPA syndrome who are carriers of the MEFV mutation, the most commonly reported mutation in ethnic groups such as the Turkish people was the M694V." (PMID 36045426, 2022). "This study evaluates the 12 common MEFV gene mutations in patients with PFAPA syndrome." (PMID 25793047, 2014). "Moreover, underlying MEFV mutations could affect periodic fever, aphthous stomatitis, pharyngitis, and adenitis (PFAPA) syndrome’s." (PMID 37848930, 2023). "DNA of patients with PFAPA syndrome was analyzed for the 3 genes associated with monogenic periodic fever (NLRP3, MEFV, and MVK) and for the AIM2 gene." (PMID 25821352, 2015). "Recent study on predominant mutations in MEFV, CARD15/NOD2, TNFr1A, and NLRP3 genes in patients diagnosed with PFAPA syndrome showed that 19 of 57 patients carried one or more of the variants tested, with MEFV gene variants being found in 16 patients." (PMID 25821352, 2015). "In the current study, the frequency of MEFV gene mutations was not higher in the responder group; therefore, there might be other mechanisms involved in the pathogenesis of PFAPA syndrome in addition to MEFV gene mutation." (PMID 36045426, 2022). "This study showed that both drug regimens are significantly effective in preventing febrile attacks in PFAPA syndrome, and the presence of a MEFV gene mutation might not be the only significant risk factor for a response to colchicine." (PMID 36045426, 2022). "Therefore, PFAPA syndrome is not unexpected in children with MEFV variants." (PMID 36777733, 2023).
AA amyloidosis (7 papers, 2016 to 2022). Secondary amyloidosis is a form of amyloidosis, that complicates chronic inflammatory disorders (mainly rheumatoid arthritis) and is characterized by the aggregation and deposition of amyloid fibrils composed of serum amyloid A protein, an acute phase reactant. "Axial involvement, coexisting heterozygous MEFV gene mutation, polyarticular subtype of PsA were observed in two patients with PsA-related AA amyloidosis." (PMID 36128216, 2022). "A serious complication of IBD and FMF is also secondary amyloidosis, and its frequency has been correlated with MEFV mutations in certain studies." (PMID 34819953, 2021). "FMF patients with two or more than two MEFV mutations had AA amyloidosis and family history of periodic fever more frequently compared with those with a single or no MEFV mutations." (PMID 27473114, 2016). "The MEFV gene variants may be screened in high-risk communities in patients with PsA-related AA amyloidosis." (PMID 36128216, 2022). "Homozygous M694V mutation in the MEFV gene causes a more severe FMF phenotype and is one of the major risk factors for AA amyloidosis." (PMID 35743929, 2022). "In the adult patient with AA amyloidosis reported hereby, an initial attempt was made of a targeted sequencing of selected exons of the MEFV gene, which proved unsuccessful." (PMID 33530412, 2021). "Furthermore, coexisting factors such as heterozygous mutant MEFV gene carriage and history of tuberculosis may have contributed to the development of AA amyloidosis." (PMID 36128216, 2022).
pericarditis (7 papers, 2014 to 2026). An inflammatory process affecting the pericardium. "Given the pattern of recurrent, steroid-responsive pericarditis with fever, an autoinflammatory mechanism was considered, and MEFV gene testing was arranged." (PMID 41523473, 2025). "Eleven variants were located in genes already associated with recurrent pericarditis (NLRP3, TNFRSF1A and MEFV) and five in inflammation/immunodeficiency-related genes (IFIH1, NFKBIA, JAK1, NOD2 and ALPK1)." (PMID 39347728, 2024). "Pericarditis is a feature of interleukin‐1 driven monogenic autoinflammatory diseases and IRP is associated with variants in MEFV, a gene involved in interleukin‐1β processing." (PMID 35658515, 2022).
autoimmune disease (6 papers, 2016 to 2025). A disorder resulting from loss of function or tissue destruction of an organ or multiple organs, arising from humoral or cellular immune responses of the individual to their own tissue constituents. "This review examines the coexistence of FMF with autoimmune diseases and metabolic disorders and explores potential correlations with MEFV mutations." (PMID 41472723, 2025). "Mutations in MEFV have been defined as variants specific to autoinflammatory diseases and have also been detected in autoimmune diseases." (PMID 37273692, 2023). "Moreover, each autoimmune disease has variable or even dominant innate immune drivers e.g. MEFV mutations in seronegative RA." (PMID 39372419, 2024).
ankylosing spondylitis (5 papers, 2013 to 2023). An autoimmune chronic inflammatory disorder characterized by inflammation in the vertebral joints of the spine and sacroiliac joints. "The aim of the present study was to comprehensively observe the contribution of several common mutations in the MEFV gene, namely, E148Q, M680I, M694V and V726A, to ankylosing spondylitis susceptibility." (PMID 28800602, 2017). "In summary, the current meta-analysis established the potential contribution of the MEFV gene mutation, M694V, to the pathogenesis of ankylosing spondylitis." (PMID 28800602, 2017). "The aim of the current study was to determine the contributions of several common mutations in the Mediterranean fever (MEFV) gene, namely, E148Q, M680I, M694V and V726A, to ankylosing spondylitis (AS) susceptibility." (PMID 28800602, 2017). "A whole-genome linkage scan detected a linkage between ankylosing spondylitis and chromosome 16p, where MEFV is located." (PMID 28800602, 2017). "Previous publications have suggested that mutations of the MEFV gene were involved in the pathogenesis of patients with HLA-B27 negative ankylosing spondylitis (AS)." (PMID 27143975, 2016).
COVID-19 (5 papers, 2020 to 2024). A disease caused by infection with severe acute respiratory syndrome coronavirus 2. "Although first results from COVID-19 patients treated with these repurposed drugs have been conflicting, the role of Pyrin (the inflammasome sensor protein that is encoded by MEFV) in modulating severity and outcome of COVID-19 is still unknown." (PMID 33072117, 2020). "The combined analysis of the presence of at least one of our two genetics biomarkers related to inflammasome activity (MEFV) and antiviral immunity (IFNAR2) was associated with an increase in COVID-19 severity risk with an OR of 6.274 (95% CI) (2.430–16.201)." (PMID 37760989, 2023). "The MEFV gene shows the highest rate of mutant alleles in some populations (Jews, Arabs, Turks, and Armenians), but COVID-19 surveillance reports indicate that the disease incidence and death rates for COVID-19 are not greater in the populations where mutant MEFV alleles predominate." (PMID 37760989, 2023).